NDUFA10 (NADH:ubiquinone oxidoreductase subunit A10)
Description:
Accessory subunit of the mitochondrial membrane respiratory chain NADH dehydrogenase (Complex I), that is believed not to be involved in catalysis. Complex I functions in the transfer of electrons from NADH to the respiratory chain. The immediate electron acceptor for the enzyme is believed to be ubiquinone.
Synonyms: CI-42kD; CI-42k; MC1DN22
Tractability: Small molecule: an approved drug acts on it; a structure with a bound ligand is known. PROTAC: ubiquitination databases record sites on it; its protein half-life has been measured; a small molecule that binds it is known.
Target class: Enzyme; Oxidoreductase
Gene: Protein-coding gene on chromosome 2 (239,892,450 to 240,025,743, reverse strand). Ensembl gene ENSG00000130414.
Subcellular location: Mitochondrion matrix
Subcellular location (Human Protein Atlas): Mitochondria
Pathways (Reactome):
Metabolism: Complex I biogenesis; Respiratory electron transport
Gene Ontology:
Molecular function: NADH dehydrogenase (ubiquinone) activity
Biological process: aerobic respiration; mitochondrial electron transport, NADH to ubiquinone; proton motive force-driven mitochondrial ATP synthesis; proton transmembrane transport
Cellular component: mitochondrial inner membrane; mitochondrion; respiratory chain complex I; cytoplasm; mitochondrial matrix
Genetic constraint (gnomAD): Loss-of-function variants: 34 observed, 40.4 expected, observed/expected ratio (o/e) 0.84, 90% interval 0.64 to 1.12. The upper end of that interval is the gene's LOEUF score, 1.12, which puts it in group 4 of 6, group 1 being the genes least tolerant of losing a copy. Missense variants: 377 observed, 420.74 expected, observed/expected ratio (o/e) 0.9, 90% interval 0.82 to 0.98. Synonymous variants: 175 observed, 165.31 expected, observed/expected ratio (o/e) 1.06, 90% interval 0.94 to 1.2.
Gene-disease validity (ClinGen):
ClinGen rates the evidence that NDUFA10 causes each of these diseases.
mitochondrial disease (autosomal recessive): Moderate.
Leigh syndrome (autosomal recessive): Limited. A progressive neurological disease defined by specific neuropathological features associating brainstem and basal ganglia lesions.
Homologues: Orthologues: chimpanzee NDUFA10 (92% identical), macaque NDUFA10 (85% identical), dog NDUFA10 (78% identical), mouse Ndufa10 (77% identical), guinea pig NDUFA10 (76% identical), rat Ndufa10l1 (76% identical), rat Ndufa10 (73% identical), pig NDUFA10 (73% identical), rabbit NDUFA10 (63% identical), zebrafish ndufa10 (56% identical), tropical clawed frog ndufa10 (55% identical), Drosophila melanogaster ND-42 (36% identical), and 1 more. Paralogues in human: DCK (17% identical), TK2 (16% identical), DGUOK (15% identical).
Diseases named in the same sentence as NDUFA10 in open-access papers:
NDUFA10 is named in the same sentence as 31 diseases in open-access papers, as found by Europe PMC text mining. Sharing a sentence is not in itself a finding about the gene and the disease. The quoted sentences say what the papers report.
Leigh syndrome (6 papers, 2019 to 2024). "The NDUFA10 gene has been linked to Leigh syndrome, a neurogenerative disease characterized by lesions in the basal ganglia and/or brainstem and deficits in motor function." (PMID 39062924, 2024). "Previous studies have also found an association between NDUFA10 and several diseases, such as nonalcoholic steatohepatitis, type 2 diabetes, Alzheimer's disease and Leigh disease." (PMID 38671439, 2024). "It is significant in this context that NDUFB10 deficiency has previously been associated with increased mtROS and compromised mitochondrial respiration, while mutations in NDUFA10 have been found in mitochondrial disorders, such as Leigh disease." (PMID 31717900, 2019). "Complex I assembly was disrupted due to mutations in NDUFA10 in individuals with Leigh syndrome." (PMID 37373264, 2023). "Hence, mutations affecting NDUFA10 stability lead to Leigh syndrome and severe isolated complex I deficiency." (PMID 35739187, 2022).
Parkinson disease (3 papers, 2017 to 2021). A progressive degenerative disorder of the central nervous system characterized by loss of dopamine producing neurons in the substantia nigra and the presence of Lewy bodies in the substantia nigra and locus coeruleus. "CI dysfunction was also reversed by expression of the phospho-mimetic Ndufa10 in cells from Parkinson’s patients carrying Pink1 mutations." (PMID 29267372, 2017).
dementia (2 papers, 2023 to 2024). Loss of intellectual abilities interfering with an individual's social and occupational functions. "The Ndufa10 gene downregulation in the brains of patients suffering from Alzheimer’s has been correlated with a higher degree of dementia." (PMID 38891920, 2024). "The lower the expression level of NDUFA10, the smaller the MMSE, and the higher the degree of dementia." (PMID 37373264, 2023). "In this paper, the gene expression of METTL3 and NDUFA10 were found to correlate with the Mini-mental State Examination (MMSE), which is a clinical indicator of the degree of dementia." (PMID 37373264, 2023).
diabetic cardiomyopathy (2 papers, 2024 to 2025). Diabetic cardiomyopathy is a disorder of the heart muscle in people with diabetes. "Ndufa10 has also been implicated in diabetic cardiomyopathy and ischemic injury." (PMID 41296444, 2025).
type 2 diabetes (2 papers, 2024 to 2025). "Among these, mitochondrial-associated proteins such as the NADH:ubiquinone oxidoreductase subunit proteins NDUFS5, NDUFA10 and NDUFS8 were downregulated in type 2 diabetes." (PMID 40295335, 2025).
Cognitive impairment (1 paper, 2024). Abnormal cognition is characterized by deficits in thinking, reasoning, or remembering. "In participants with cognitive impairment, the expression levels of KEGG:M00146’s NDUFA2, NDUFA3, NDUFA4, NDUFA6, NDUFA7, NDUFA10, and NDUFA12 increased, but the expression levels of NDUFA5, NDUFA4L2, and NDUFAB1 marginally decreased." (PMID 38542318, 2024).
COVID-19 (1 paper, 2020). A disease caused by infection with severe acute respiratory syndrome coronavirus 2. "Several mitochondrial genes, for instance NDUFA10, NDUFAF5, and SAMM50 were downregulated in COVID-19-affected lung." (PMID 33173052, 2020).
lung adenocarcinoma (1 paper, 2024). A carcinoma that arises from the lung and is characterized by the presence of malignant glandular epithelial cells. "Accordingly, a study conducted by Jeon and colleagues has shown that an elevated expression of OXPHOS-encoding genes, in particular genes of core, accessory, and assembly subunits of Complex I, including NDUFS2 and NDUFA10, correlates with poor prognosis in lung adenocarcinoma patients." (PMID 39000504, 2024).
oral cancer (1 paper, 2020). "Although in this experiment we did not detect significantly altered expressions of NDUFA10 and SDHD, their significant synergism in PTC may explain why they are both up-regulated in oral cancer." (PMID 32887258, 2020).
prostate carcinoma (1 paper, 2021). A carcinoma that arises from epithelial cells of the prostate gland. "Mitochondrial-related genes including NDUFA10 and NDUFV2 participate in androgen regulation and may be candidate prognostic markers, which could be therapeutic targets of prostate cancer." (PMID 34124242, 2021).
schizophrenia (1 paper, 2016). A major psychotic disorder characterized by abnormalities in the perception or expression of reality. "In this study, NDUFA10 in HyDEN has found to be associated with the abnormalities of mitochondrial function in schizophrenia." (PMID 28117656, 2016). "NDUFA10 has been contributed to the abnormalities of mitochondrial function in schizophrenia." (PMID 28117656, 2016).
viral infection (1 paper, 2020). "Similar to EEF1A1, the NDUFA10 protein network is downregulated by viral infection." (PMID 32244779, 2020).
cancer (3 papers, 2020 to 2025). A tumor composed of atypical neoplastic, often pleomorphic cells that invade other tissues. "Among the core genes, NDUFA10 showed a low expression value in cancer patients across different expression profiles, while NDUFV2 showed a high expression value in cancer patients." (PMID 34124242, 2021). "Machine learning models based on seven LM-related genes (CHEK2, LIPT1, TUFM, NDUFA10, AGK, PNPLA2, and GFM1) accurately predicted immunotherapy outcomes for multiple cancer types, including LUSC, and outperformed other currently known biomarkers." (PMID 40568577, 2025). "In addition, we found in this list established cancer genes involved in other types of cancer, such as PDE4DIP, SF3B1, AHNAK, COPB2, CSDE1, KIF5B, NDUFA10, RSRC2." (PMID 31949199, 2020).
neurodegenerative disease (2 papers, 2023 to 2025). A disorder of the central nervous system characterized by gradual and progressive loss of neural tissue and neurologic function. "NDUFA10 is an accessory subunit of the mitochondrial respiratory chain complex I. Mutations in subunits of complex I can cause a variety of defects, such as reactive oxygen species production, neurodegenerative diseases, apoptosis, and cell death." (PMID 37373264, 2023). "Abnormal expression of NDUFA10 contributes to the assembly disorder of mitochondrial complex I and affects the electron respiratory chain, contributing to several neurodegenerative diseases." (PMID 41374081, 2025).
tumor (2 papers, 2021 to 2025). "The expression values of NDUFA10 in normal samples were higher than that in tumor samples." (PMID 34124242, 2021).
NDUFA10 also shares sentences with these, for which no sentence is quoted: Alzheimer disease (2 papers); neurological diseases (2); brain diseases (1); cardiac hypertrophy (1); cardiomyopathies (1); Dystonia (1); Huntington disease (1); Hypertension (1); hypertrophic cardiomyopathy (1); ischemia (1); memory impairment (1); mitochondrial disease (1); neurodevelopmental disorder (1); nonalcoholic steatohepatitis (1); OXPHOS disease (1); Parkinson’s (1).